EGFR (epidermal growth factor receptor)
Diseases named in the same sentence as EGFR in open-access papers (continued):
Sharing a sentence is not in itself a finding about the gene and the disease.
lung adenocarcinoma (continued). "In two phase 3 clinical trials, LUX-Lung 3 and LUX-Lung 6, the median PFS among patients of lung adenocarcinoma harboring EGFR mutations taking 40 mg afatinib as their initial dose was 10.9 and 13.6 months, respectively." (PMID 33941115, 2021). "The role of EGFR K860I mutation in lung carcinogenesis is unclear, and this case reports a patient with lung adenocarcinoma harboring a rare uncommon EGFR mutation." (PMID 33942527, 2021). "As EGFR sensitive mutations were more likely to occur in lung adenocarcinoma, our incidence was higher than previously reported Chinese NSCLC patients (46.05% vs. 34.8%)." (PMID 33997043, 2021). "In the Asian ethnicity, mutations in the epidermal growth factor receptor (EGFR) gene occur in ~ 50% of all lung adenocarcinomas." (PMID 33942501, 2021). "Further study is warranted to understand the effect of different 2nd-ling therapy on OS in patients receiving 1st-line afatinib for their lung adenocarcinoma harboring EGFR mutation." (PMID 33941115, 2021). "In particular, lung adenocarcinomas with mutations in the gene encoding the epidermal growth factor receptor (EGFR) are uniquely sensitive to EGFR blockade with specific tyrosine kinase inhibitors (TKIs)." (PMID 34367939, 2021). "Epidermal growth factor receptor (EGFR)-tyrosine kinase inhibitors (TKIs) show efficacy in treating patients with lung adenocarcinoma with EGFR-activating mutations." (PMID 34036228, 2021). "The highest prevalence of EGFR mutations (30–38%) occurs in lung adenocarcinoma patients of Southeast Asian ethnicity, including Japan and China." (PMID 34202748, 2021). "These lung adenocarcinoma patients were divided into patients with EGFR wild type (n = 127, 40.2%) and patients with EGFR mutation (n = 189, 59.8%) based on EGFR sequencing data." (PMID 34948746, 2021). "This study aimed to compare the relative survival rate of gefitinib, erlotinib, and afatinib in patients with EGFR-mutated advanced lung adenocarcinoma by real-world data in Taiwan." (PMID 34434112, 2021). "We evaluated the risk of recurrence based on co-occurring actionable mutations, the number of co-mutations, EGFR mutation types, and EGFR exon 19 deletion (19-del) subtypes in resected EGFR-mutated lung adenocarcinomas." (PMID 34298845, 2021). "Activating epidermal growth factor mutations (EGFR) are found in approximately 10% of the Caucasian and 50% of the Asian patients with lung adenocarcinoma." (PMID 34201833, 2021). "45.7% of Chinese patients with advanced lung adenocarcinoma were reported to harbour sensitizing epidermal growth factor receptor (EGFR) mutations." (PMID 34628779, 2021). "Subsequently, the phase 3 FLAURA study compared osimertinib to either erlotinib or gefitinib in frontline therapy for EGFR-mutated lung adenocarcinoma." (PMID 34202748, 2021). "In conclusion, the immunohistochemistry test has shown excellent specificity, however, with low sensitivity in the detection of the most common EGFR gene mutation in a series of primary lung adenocarcinoma cases." (PMID 34181354, 2021). "Next, we examined the expressions of YAP and p62 in lung adenocarcinoma patients who have EGFR mutations using Chungnam national university hospital patients’ samples." (PMID 33486901, 2021). "The BEYOND study showed that OS was increased by 6.6 months (24.3 vs. 17.7 months) and ORR was increased by 28% (54% vs. 26%) in a group of unselected lung adenocarcinoma patients (including some EGFR-sensitive mutation-positive patients)." (PMID 33575349, 2021).
lung adenocarcinoma (continued). "The accompanying concurrent mutations clearly provide an impact on recurrence in resected EGFR-mutated lung adenocarcinoma as the EGFR- mutated lung adenocarcinoma with more concurrent mutations had poorer response rate to EGFR-TKIs in advanced stages." (PMID 34298845, 2021). "The discovery of activating mutations of the epidermal growth factor receptor (EGFR) in patients with lung adenocarcinoma led to the development of a new family of biological agents, called tyrosine kinase inhibitors (TKIs)." (PMID 33435440, 2021). "EGFR mutations occur most often in lung adenocarcinomas and play an important part in mediating global metabolic reprogramming." (PMID 34745994, 2021). "Within the present study, we aimed for a comprehensive and translational approach to systematically characterize the role of co-occurring EGFR/BRAF mutations in patients with advanced lung adenocarcinoma." (PMID 34921211, 2021). "Lineage transformation from lung adenocarcinoma (LUAD) to SCLC is associated with resistance to EGFR tyrosine kinase inhibitors." (PMID 35005656, 2021). "Extensive somatic mutations in the EGFR gene were observed in Caucasian and East Asian lung adenocarcinoma (LUAD) patients (approximately 10% and 50%, respectively)." (PMID 34250747, 2021). "Studies have estimated that ~5–15% of EGFR-mutated lung adenocarcinomas treated with EGFR TKIs transform to SCLCs." (PMID 34572868, 2021). "Both wild-type and mutated EGFR lung adenocarcinoma specimens had enhanced expression of EGFR in pleural endothelial cells." (PMID 34680445, 2021). "Together, these results suggest that IL-8-CXCR1/2 signaling is associated with gefitinib resistance, thus providing a possible mechanism whereby high plasma IL-8 levels mediate PFS in EGFR TKI-treated patients with EGFR mutation-positive lung adenocarcinoma." (PMID 33466795, 2021). "To better understand the biology of the EGFR-mutated lung adenocarcinomas we compared copy number profiles between EGFR-mutated and wild type tumors." (PMID 34625038, 2021). "EGFR-TKIs have a high efficacy in patients with lung adenocarcinoma and an EGFR mutation and bone metastases." (PMID 34201833, 2021). "Currently, CSCs can acquire resistance to EGFR (Epidermal growth factor receptor) inhibitors, which is an effective therapy for lung adenocarcinoma patients with activating mutations, making effective therapy more difficult." (PMID 34059086, 2021). "We first revealed an association between miR‐1 expression, TIME, and EGFR‐TKI resistance in lung adenocarcinoma patients." (PMID 33305905, 2021). "Transformation to SCLC is observed in approximately 5–14% of patients with lung adenocarcinoma carrying EGFR activating mutations." (PMID 33922215, 2021). "Epidermal growth factor receptor (EGFR)-activating mutations represent the most frequent targetable alteration with a prevalence of nearly 20% in Caucasians with lung adenocarcinomas (ADCs) and show sensitivity to various TKIs." (PMID 34487971, 2021). "We present a case of a woman with epidermal growth factor receptor (EGFR)-mutated lung adenocarcinoma who received gefitinib for 2 years and obtained a partial response." (PMID 34590588, 2021). "The present study showed that the mutation rate of EGFR (55.6%) in lung adenocarcinoma of TNM stage I-II was similar to that in stage III-IV (56.5%)." (PMID 33707479, 2021). "Subsequently, the patient was diagnosed with stage IV lung adenocarcinoma with an EGFR exon 19 deletion mutation (cT2N2M1 according to TNM classification, version 8)." (PMID 34397927, 2021). "This led to the identification of 15 patients with lung adenocarcinoma harboring activating EGFR mutations and co-occurring BRAF mutations." (PMID 34921211, 2021). "Epidermal growth factor receptor (EGFR) mutations, which are detected in up to 50% of patients with lung adenocarcinoma, are recognized as the major actionable target in Asians." (PMID 33466795, 2021).
lung adenocarcinoma (continued). "In the sequence, we observed the response of human lung adenocarcinoma with EGFR mutation to gefitinib and dasatinib in the PDX model." (PMID 34367939, 2021). "In this study, the effects of cisplatin in lung adenocarcinoma cell lines harboring clinically relevant mutations, such as EGFR mutations, were studied." (PMID 34966671, 2021). "The overlap between PD-L1 expression and EGFR mutations is still considerable based on the results from a previous study in Chinese lung adenocarcinoma patients." (PMID 35003359, 2021). "Herein, we report a lung adenocarcinoma patient harboring a rare EGFR E709_T710delinsD mutation who was treated with afatinib as the first-line therapy and achieved a progression-free survival of 23 months." (PMID 34178699, 2021). "The elderly patient in our report, who presented with lung adenocarcinoma with an uncommon EGFR mutation, developed a long‐term response to afatinib with appropriate dose reduction." (PMID 33533191, 2021). "Although the majority of patients with lung adenocarcinoma harboring sensitizing EGFR mutations respond to EGFR-TKIs including osimertinib, efficacy is limited by the universal development of acquired resistance." (PMID 34568058, 2021). "A 70-year-old female diagnosed with “ lung adenocarcinoma with intracranial metastasis” harboring a mutation of EGFR 19DEL was administrated with Almonertinib 110 mg orally as the first-line treatment." (PMID 33546082, 2021). "As the clinical behavior of EGFR-mutated lung adenocarcinoma resembles metastatic breast and prostate cancer, with a real possibility for prolonged survival, data for this subgroup is also needed." (PMID 34201833, 2021). "Percutaneous lung biopsy confirmed adenocarcinoma on November 19, 2018, and he was clinically diagnosed with stage IVa lung adenocarcinoma (cT1cN1M1b) with an EGFR 19del mutation, detected through the Next Generation Sequencing (NGS) platform." (PMID 34160440, 2021). "USP22 is shown to regulate EGFR endocytosis through deubiquitination, resulting in sustained activation of the EGFR-dependent signaling pathway and promoting resistance to EGFR-TKIs in EGFR-mutated lung adenocarcinoma." (PMID 33805973, 2021). "Collectively, these trials established EGFR TKIs as front-line treatments in locally advanced and metastatic (stage IV) lung adenocarcinoma with sensitizing EGFR mutations." (PMID 34202748, 2021). "Patients with lung adenocarcinomas carrying EGFR mutations (mainly exon-19 deletion and L858R) showed positive responses towards TKIs such as Gefitinib and Afatinib, the first and second generations of TKIs." (PMID 34885115, 2021). "NGS achieved an accuracy of 99.1% for detecting EGFR mutation in patients with advanced lung adenocarcinoma, compared with the traditional Sanger sequencing method." (PMID 33920322, 2021). "One of the strong points in our current study was that it did not include physician selection bias as we included specimens from most of the EGFR-mutated lung adenocarcinomas resected at our institution over nearly a 12-year period." (PMID 34298845, 2021). "A 62-year-old woman with rheumatoid arthritis and a history of receiving immunosuppressant therapy had a recurrence of lung adenocarcinoma with EGFR L858R mutation." (PMID 33755322, 2021). "The emergence of a broad class of potent EGFR TKIs has revolutionized the management of EGFR-mutated lung adenocarcinoma." (PMID 34202748, 2021). "Tissues from 131 patients who had complete resection of stage I–IIIA EGFR-mutated lung adenocarcinoma were analyzed by targeted NGS for 207 cancer-related genes." (PMID 34298845, 2021). "Patients with EGFR-mutated lung adenocarcinoma of more advanced stage in our cohort had shorter RFS than that previously reported (p < 0.001)." (PMID 34298845, 2021). "Here it is reported the case of a young patient affected by lung adenocarcinoma harboring the L858R EGFR sensitive mutation." (PMID 34178662, 2021).
lung adenocarcinoma (continued). "Dual inhibitors for intrinsic apoptosis and necroptosis completely rescued the cell deaths of EGFR-mutated lung adenocarcinoma cells (Annexin V-positive: apoptosis; PI-positive: necroptosis)." (PMID 34367939, 2021). "A total of 82 patients with advanced lung adenocarcinoma harboring EGFR exon 18 mutations were included in the final analysis." (PMID 34540680, 2021). "Although the mechanism is not elucidated in GC, loss of NF1 has been associated with resistance to EGFR TKIs in lung adenocarcinomas and resistance to BRAF inhibitor in melanoma by increasing MAPK and/or PI3K signaling via negatively regulating Ras." (PMID 34399705, 2021). "Brain metastases (BMs) occurred in 25-50% of non-small-cell lung cancer (NSCLC) patients, 30-60% of those had epidermal growth factor receptor (EGFR) activating mutation lung adenocarcinoma (LADC)." (PMID 33828979, 2021). "Lung adenocarcinomas with EGFR mutation comprise a specific clinical subtype and are more frequent in women, never-smokers and patients with Asian ethnicity." (PMID 34625038, 2021). "Bone metastases with their risk of SRE development and resulting impact on QoL, can become a clinically relevant problem in patients with lung adenocarcinoma and an EGFR mutation because of their prolonged post-bone metastases diagnosis survival." (PMID 34201833, 2021). "We retrospectively enrolled a total of 323 lung adenocarcinoma patients (164 had EGFR mutations), and their corresponding tissue samples were analyzed by the EGFR mutation test and immunohistochemistry." (PMID 34484468, 2021). "Concurrent genetic alterations were detected in 5.4% of lung adenocarcinoma patients, and EGFR mutations were observed as the most common partner for concurrent genetic alteration." (PMID 34234236, 2021). "The accurate identification of tumors with sensitized EGFR mutations, the most common targetable molecular alteration in lung adenocarcinoma, and acquired drug resistance mutations during treatment is a clinical priority." (PMID 33828979, 2021). "Epidermal growth factor receptor-mutated non-small-cell lung cancer (EGFR+ NSCLC) comprises about 10%–15% of lung adenocarcinomas." (PMID 33898315, 2021). "From June 1, 2016 to December 31, 2018, a total number of 1180 advanced patients with EGFR mutation lung adenocarcinoma were screened." (PMID 33975616, 2021). "Lung adenocarcinomas that are responsive to epidermal growth factor receptor (EGFR) tyrosine kinase inhibitors possess EGFR mutations and often increased EGFR CNs." (PMID 34259866, 2021). "This study included 131 patients with stage I to stage IIIA EGFR-mutated lung adenocarcinoma whose tumors were resected from 2005 to 2017." (PMID 34298845, 2021). "ATG10rs1864182 was also shown to serve as biomarker for primary or acquired resistance to chemotherapy when using gefitinib (an epidermal growth factor receptor (EGFR)-TKI drug) in advanced lung adenocarcinoma patients with EGFR mutations." (PMID 33809750, 2021). "The present study demonstrates that ddPCR can detect EGFR mutations in primary lung adenocarcinoma with high sensitivity (80.0%) and high specificity (100%) in SC (+) cases." (PMID 33757469, 2021). "In general, the EGFR mutation frequency of synchronous MPLAs was higher than that of the single Asian lung adenocarcinoma population in the PIONEER study (51.4%)." (PMID 34804960, 2021). "Among the oncogenic drivers of a lung adenocarcinoma, activating mutations within the EGFR tyrosine kinase domains account for approximately 17% of these diagnoses." (PMID 34439090, 2021). "Our study aimed to investigate the prognostic factors in patients with BM from epidermal growth factor receptor (EGFR) mutation-positive lung adenocarcinoma." (PMID 34577890, 2021).
lung adenocarcinoma (continued). "The ORA-based screening of the WGCNA modules was performed to capture clinically important modules and their upstream regulators, which reflect the disease mechanisms affected differentially under the different driver EGFR mutations in lung adenocarcinoma." (PMID 32983988, 2020). "Collectively, our study reveals B7-H3-induced signaling in lung adenocarcinoma cell lines with divergent EGFR mutations, and a translational potential of combined targeted therapy of B7-H3 and EGFR in lung adenocarcinoma with EGFR Del E746-A750 mutation." (PMID 33426073, 2020). "Tumor surface programmed death-ligand 1 (PD-L1) is expressed in some metastatic EGFR-mutated lung adenocarcinoma, but its impact on the efficacy of EGFR-TKIs is unclear." (PMID 32092879, 2020). "We conducted this study to investigate the utility of radiomic features of 18F-FDG PET in predicting the survival in patients with primary advanced EGFR-mutated lung adenocarcinoma treated with TKIs." (PMID 33370365, 2020). "Two EGFR mutations, an in-frame deletion within exon 19 and the L858R point mutation in exon 22, account for approximately 90% of overall EGFR mutations in lung adenocarcinoma." (PMID 32781755, 2020). "On the opposite, germline EGFR missense variants, such as T790M, V834L and V843I, have been associated with rare cases of familial lung adenocarcinoma." (PMID 32365798, 2020). "PD-L1 expression does not affect the efficacy of first-line EGFR-TKIs in untreated stage IV EGFR-mutated lung adenocarcinoma." (PMID 32092879, 2020). "The Kirsten rat sarcoma (KRAS) and epidermal growth factor receptor (EGFR) mutations play an important role in the pathogenesis of most lung adenocarcinomas and are, with rare exceptions, mutually exclusive, and vary by geography." (PMID 33194700, 2020). "In Spain, epidermal growth factor receptor (EGFR) mutations are present in 8–11% of advanced NSCLCs, and in 16–18% of lung adenocarcinomas." (PMID 31598903, 2020). "In our results, 190 patients with EGFR-mutated lung adenocarcinoma under TKI treatment demonstrated that patients with higher pretreatment platelet counts had shorter PFS and OS." (PMID 32702917, 2020). "Outcomes of lung adenocarcinoma patients receiving EGFR TKIs were reported to be affected depending on the types of EGFR gatekeeper mutation, which are serious clinical challenges." (PMID 32983988, 2020). "Applying this knowledge, the phase III I-PASS trial selected East Asian patients with lung adenocarcinoma and minimal smoking history and demonstrated that only EGFR-mutated patients benefited from gefitinib." (PMID 33364187, 2020). "The aim of this study was to develop a radiogenomic approach to identify EGFR mutations in advanced lung adenocarcinoma non-invasively." (PMID 32082997, 2020). "Our results contribute to the growing evidence that B7-H3-induced signaling promotes cell survival and reduces gefitinib sensitivity of lung adenocarcinoma cells with mutant EGFR alleles." (PMID 33426073, 2020). "Since Chinese patients with lung adenocarcinoma have a much higher rate of EGFR mutations than Caucasians, researchers evaluated Chinese patients treated with single‐agent ICIs and found that EGFR/ALK alterations were associated with HPD." (PMID 32997401, 2020). "In conclusion, younger age, initially metastatic disease, and metastasis to the brain or another lobe of the lung were associated with LMC in patients with lung adenocarcinoma harboring EGFR mutation." (PMID 31910497, 2020). "Lung adenocarcinoma cell lines with activating EGFR mutation such as EGFRL858R or exon 19 deletion, strongly respond to gefitinib." (PMID 33205120, 2020). "Fifty-one patients with stage III-IV lung adenocarcinoma and actionable EGFR mutation who received first-line TKI were retrospectively analyzed." (PMID 33370365, 2020). "For example, the EGFR mutation rate in patients with lung adenocarcinoma in Europe and the United States is only 10%–17%, but in Asian patients it is 30%–65%." (PMID 32944405, 2020).